IL6 (interleukin 6)
Diseases named in the same sentence as IL6 in open-access papers (continued):
Sharing a sentence is not in itself a finding about the gene and the disease.
Obesity (continued). "Chronic inflammation, marked by raised serum interleukin 6 (IL-6), C-reactive protein (CRP) and tumor necrosis factor alpha (TNF-α), anemia and lower hematocrit levels, immune activation, as well as obesity and other comorbidities have also been defined as etiologies of frailty." (PMID 34574503, 2021). "And computational analysis suggested that metformin may effectively dock with 1ALU, 5T1A residues in IL-6, CCL2 proteins in obesity and hypertension." (PMID 34334083, 2021). "The increased levels of IL-6 and TNF-α in obesity could also affect endothelial NO synthase expression." (PMID 34436493, 2021). "Similarly, in our previous study, we did not observe the significant differences between serum levels of CRP, TNF-α, IL-1, and IL-6 of girls with PCOS and normal weight compared to the group with overweight and obesity." (PMID 33849511, 2021). "↑CD68 marker in obesity and in T2DM.↓CD11b, CD11c, CD163 and CD169 in T2DM patients↑TNFα, iNOS, IL-6, CD16, CD36, and CD206 in the T2DM Metformin restored TNFα, iNOS, IL-6, CD11c, CD36, CD169 and CD206 in T2DM patients to levels equivalent to those of lean volunteers." (PMID 34163481, 2021). "The hypothesis of this study is that individuals with obesity are more likely to have elevated leptin levels and inflammatory markers (including CRP, IL‐6, TNF‐α)." (PMID 33680494, 2021). "Concomitantly, markers of endothelial dysfunction correlated with cytokines levels of the Th1 immune orientation (IFNγ, TNFα), inflammation (IL-17a, MIP1α, G-CSF, TNFα, MIP1β, and IFNγ), and/or M1 activation (IL-6, IFNγ, TNFα, IP10, MIP1α, and MCP1), mostly in patients with obesity." (PMID 34038475, 2021). "Next, we decipher a potential molecule (IL-6), which showed homologous alterations in WAT in both obesity and lipolysis and might have a role in ATM remodeling." (PMID 34504646, 2021). "The infiltration of expanded adipose tissue by macrophages, which are responsible for both the generation of inflammatory signals and the production of cytokines such as IL-6 and TNF-α, could explain the rise in CRP in obesity." (PMID 34680097, 2021). "Increased levels of C-reactive protein (CRP), a serum acute-phase reactant produced by the liver, and other proinflammatory cytokines secreted by the adipose tissue such as interleukin-6 (IL-6) and tumor necrosis factor-α (TNF-α), have been reported in patients with obesity." (PMID 33919641, 2021). "The present study demonstrated that 12 weeks of synbiotic supplementation significantly reduced the physical parameters as well as the inflammation markers IL-6, IL-1β, TNF-α and other obesity markers including LPS, zonulin, 5-HIAA, and QA in Thai obese subjects." (PMID 34359450, 2021). "It is known that (pre)adipocytes, a predominant cell type present in the adipose tissues, express and secrete a variety of adipokines (leptin, adiponectin, etc.)as well as inflammatory cytokines (TNF-α, IL-1β, IL-6, etc.)and enzymes (iNOS, COX-2, etc.), which confer obesity inflammation." (PMID 34063048, 2021). "The immune dysregulations include increased levels of inflammatory markers such as C - reactive protein (CRP), interlukin-6 (IL-6), tumour necrosis factor alpha (TNF alpha), and other cytokines indicating insulin and leptin resistance, obesity, inflammation, and higher rates of metabolic syndrome." (PMID 34895175, 2021). "Furthermore, excessive cytokines, such as interleukin (IL)-6, IL-8, monocyte chemoattractant protein-1 (MCP-1), and leptin produced by the dysfunctional adipocytes in obesity, leads to increased recruitment of macrophages." (PMID 33546633, 2021). "IL-6 and TNF-α are classic obesity-related inflammatory factors." (PMID 34836242, 2021). "Paradoxically, IL-6/STAT3 signaling was required for M2-like ATM proliferation in obesity and could thus retard obesity-related insulin resistance in mice." (PMID 34504646, 2021).
Obesity (continued). "Being skewed toward a proinflammatory state, alterations in adipocyte-intrinsic cellular metabolism impacts adipocyte-immune cell crosstalk via changes in adiponectin, leptin, and IL-6, as well as other pro-inflammatory mediators (e.g., TNF, IL-1, type I IFNs, etc.)is dysregulated during obesity." (PMID 33958704, 2021). "In obesity and diabetes, there is evidence that exposure to PM 2.5 alters endothelial function, increasing serum levels of tumor necrosis factor alpha (TNF-a), as well as higher levels of interleukin-6 (IL-6), resistin, and leptin." (PMID 34367051, 2021). "Based on the importance of IL-6 in regulating NASH and HCC, in principle, the IL-6 blockade might be beneficial in obesity-induced liver cancer." (PMID 33671547, 2021). "However, in accordance with our results, in 22 patients with obesity and impaired glucose homeostasis, CRP and IL-6 levels decreased 1 month and 6 months after SG13." (PMID 34108550, 2021). "Several studies have reported sexual dimorphism in IL-6 in situations of severe injury, stress, and infection, but not in obesity." (PMID 34439950, 2021). "Therefore, our data indicated the existence of an aberrant interplay between IL-6 and IDO1 in obesity and the possibility to use IL-6R blockers for therapeutic purposes in obese patients." (PMID 34394118, 2021). "It is considered that IL-6, together with TNF-α, could play a key role in developing insulin resistance and pathologies related to obesity." (PMID 34568404, 2021). "In animal models of obesity and insulin resistance it was shown that the inhibition of FABP4 protein in macrophages reduces inflammatory cytokines (MCP-1, IL-1β, IL-6 and TNFα) and the formation of atherosclerotic lesions and foam cells and improves insulin sensitivity." (PMID 34834808, 2021). "Furthermore, an increase in obesity-induced lipid storage leads to adipose tissue dysfunction and promotes adipocyte secretion of pro-inflammatory cytokines, including TNF-α and IL-6." (PMID 34194325, 2021). "Adipokines, including IL-6 and TNF-α, are reported to induce inflammation in obesity." (PMID 34074279, 2021). "In patients with obesity, overproduction of cytokines evokes a preexisting chronic inflammation, since adipocytes secretion of pro-inflammatory molecules (e.g. MCP-1, IL-6, IL-18, TNF-α, IL-1β) together with a decrease of anti-inflammatory cytokines (e.g. IL-10) has been reported." (PMID 34038475, 2021). "In accordance, elevated TNF-α and IL-6 independently predict incident HFpEF, the predominant type of HF in obesity and diabetes, but not HF with reduced ejection fraction (HFrEF)." (PMID 34671656, 2021). "Inflammatory diseases, such as obesity, type 2 diabetes mellitus, and periodontitis induce the production of pro-inflammatory cytokines, such as Tumor Necrosis Factor alpha (TNF-α), IL-1, and IL-6, influencing the involvement and progression of each other." (PMID 33802889, 2021). "Increasing obesity induces the release of chemotactic molecules (e.g., monocyte chemoattractant protein-1) with macrophage infiltration and the release of proinflammatory cytokines, such as TNF-α and IL-6." (PMID 34065158, 2021). "Indeed, AMY1 was significantly decreased and the obesity-related salivary biomarkers resistin, MCP-1, TNF-α, IL-6 and CRP were significantly increased in overweight/obese children compared with normal weight children." (PMID 34444230, 2021). "In contrast, a study in 39 patients with obesity reported no significant changes in IL-6 or IL-8 serum concentrations 6 months after bariatric surgery, ascribable to a compensatory effect of physical activity." (PMID 34108550, 2021). "Furthermore, to evaluate the potential of SIT to attenuate obesity induced inflammation and thus insulin resistance, we quantified the gene and protein expression of proinflammatory cytokines including TNF-α and IL-6 in the adipose tissues of rats under study." (PMID 33917607, 2021).
Obesity (continued). "We have also observed similar findings in this study, whereby TNF-α, IL-6, IL-8, MIF and PIA-1 were significantly associated with OSA was independent of the degree of obesity." (PMID 34086720, 2021). "It has been reported that individuals with obesity have higher concentrations of MCP-1 when compared to non-obese controls, with a positive association of MCP-1 with CRP and IL-6, and a negative association with HDL-C." (PMID 34822430, 2021). "In the present study, we investigated the possible relationship between IL-6 and IDO1 in obesity." (PMID 34394118, 2021). "IL-6–mediated inflammation in obesity is source-specific, and the IL-6 secreted by adipocytes or infection of non-resident adipocyte cells, including adipose tissue macrophage (ATM) and T cells in a non-canonical mechanism." (PMID 34220807, 2021). "However, when the amount of VAT and SAT have been measured by computerized tomography (CT), or by magnetic resonance imaging (MRI), some studies suggest that IL-6 levels are more strongly linked to VAT than to other indices of obesity, while others could not confirm that finding." (PMID 33604566, 2021). "Elevated CRP correlates with interleukin (IL)–6, tumor necrosis factor (TNF)–α, obesity or insulin resistance, which may indicate a link between chronic inflammation and endothelial dysfunction." (PMID 33806236, 2021). "In our study, IL-6 did not have a significant correlation with obesity parameters but in another study, IL-6 was significantly greater in obese women with PCOS compared to lean women with PCOS." (PMID 33997590, 2021). "Obesity has been shown to be associated with the production of dysregulated cytokines and augment the synthesis of acute-phase reactants, such as IL-6, IL-8, TNF-α, C-reactive protein (CRP), and monocyte chemotactic protein-1 (MCP-1) in patients with obesity and various animal models of obesity." (PMID 34220807, 2021). "Another study with same model, showed that CD11c+ cell ablation results in the reduction of CLS formation with increased Il10 and decreased Il6 and Mcp1 expression in VAT.These results indicate the crucial role of ATDCs to activate CD4+ T cells that contributes to AT inflammation in obesity." (PMID 34445379, 2021). "The possible mechanisms may be due to obesity-related molecules, such as leptin, adiponectin, TNF-α, and IL-6, and their subsequent signal pathways." (PMID 33842335, 2021). "In humans, umbilical cord blood from babies born to mothers with obesity exhibited reduced esoinophils and CD4+ T cell counts, decreased monocyte and dendritic cell (DC) response to TLR ligands, and increased cord blood plasma IFNα2 and IL-6." (PMID 35126181, 2021). "PCOS is a low-grade inflammatory state; women with PCOS have higher levels of inflammatory markers such as C reactive protein (CRP), tumor necrosis factor α (TNF-α), and interleukin 6 (IL6), independent of associated obesity." (PMID 33746952, 2021). "Most studies investigating the role of inflammation in obesity have used CRP and/or IL-6." (PMID 33604566, 2021). "Moreover, various other fatty tissue products have been characterized, such as TNF-α, IL-6, IL-1, CCL2, and plasminogen activator inhibitor type-1, which play a crucial role in immune dysregulation in individuals with obesity." (PMID 34220807, 2021). "Furthermore, increased levels of IL-6 and TNF- α have been reported both in depressed patients and in those with obesity." (PMID 33809270, 2021). "Blood and tissue inflammatory cytokine levels including either TNF-α, IL-1b, IL-6, IL-10, or MIP-2a were also increased with obesity in 22 of 30 cases and may have contributed to inflammatory organ injury and worsened survival." (PMID 32211204, 2020). "Obesity is related to increases in the levels of insulin, insulin-like growth factor (IGF), and adipocyte-derived factors such as tumor necrosis factor (TNF)-alpha, leptin, and interleukin (IL)-6 and a decrease in levels of adiponectin." (PMID 32466596, 2020).
Obesity (continued). "Pro-inflammatory markers, such as interleukin-6 (IL-6), tumor necrosis factor α (TNFα), and C-reactive protein (CRP), elevate in response to infection, tissue damage, and in active stressed states such as obesity." (PMID 33004039, 2020). "Furthermore, breast cancer patients with obesity are less sensitive to anti VEGF treatment and they have increased systemic concentrations of IL-6 and fibroblast growth factor-2 (FGF-2)." (PMID 33339340, 2020). "In obesity, adipokines are dysregulated, whereby inflammatory cytokines such as TNF-α, IL-6, IFN-γ, and IL-1β are upregulated, resulting in a state of chronic low-grade inflammation called metabolic inflammation which underlies pathophysiology of obesity and metabolic syndrome." (PMID 32403230, 2020). "A long period of EGCG treatment reduced obesity development, and symptoms related to metabolic diseases and fatty liver through reduced lipid absorption and decreased inflammatory cytokines such as TNF-α, IL-1β, and IL-6." (PMID 32641048, 2020). "In the persistently slight inflammation situation induced by obesity and liver fat infiltration, the concentrations of inflammatory adipokines such as TNF-α and IL-6 increased and aggravated IR further, while simultaneously caused the inhibition of ADP production and secretion." (PMID 32054179, 2020). "In obesity, the MCP-1 secreted by both hypertrophic adipocytes and M1 macrophages has been reported to accelerate macrophage infiltration into the adipose tissue and increase adipose tissue-derived IL-6 and IL-1β levels." (PMID 32019160, 2020). "However, Il-6 can also induce oxidation of FFA and adipose tissue browning in animal models of obesity." (PMID 32397353, 2020). "Hence, our results showed that with obesity triggered dysmetabolism, hyperglycemia and hypertriglyceridemia, as well as an increase of the levels of inflammatory cytokines (TNF-α, IL-6), are present." (PMID 32795274, 2020). "However, adipocytokine secretion is strongly influenced by obesity, with higher TNF-α, IL-6 and leptin and lower adiponectin levels in adipocytes from morbidly obese subjects than from non-obese subjects." (PMID 32244787, 2020). "In research studies about obesity, acupuncture could regulate inflammatory cytokines, such as TNF-α, IL-6, and IL-1β and inflammatory cells, such as macrophages." (PMID 32595736, 2020). "We have analyzed the putative interaction between AD transgenes and HFD-induced obesity in a widely used AD mouse model, with and without the blocking of IL-6 trans-signaling in the brain." (PMID 32630818, 2020). "Furthermore, the adipose tissue of patients with metabolic syndrome and obesity produces inflammatory cytokines, particularly tumor necrosis factor (TNF) and interleukin-6 (IL-6)." (PMID 33143256, 2020). "In obesity, adiponectin levels are found to be reduced, given that its expression is inhibited by hypoxia, oxidative stress, insulin resistance, TNF-α, IL-6, “catecholamine resistance”, fetuin A, and SeP." (PMID 32604889, 2020). "Furthermore, a low-grade, chronic inflammation develops with aging and obesity, as indicated by higher circulating concentrations of C-reactive protein (CRP) and interleukin 6 (IL-6)." (PMID 31963377, 2020). "While there is no apparent correlation between serum IL-6 levels and age, elevated circulating concentrations of IL-6 are commonly observed in obesity and diabetes, as a symptom of chronic low-grade inflammation." (PMID 32365896, 2020). "Further studies determining whether specific bacterial species can modulate WAT IL-6 production are warranted, as interventions that could reduce WAT IL-6 expression in obesity may provide an avenue for preventing insulin resistance and type 2 diabetes." (PMID 32831895, 2020). "Moreover, in adults (aged 45–84 years), in a population study of 6,814 participants with a median follow-up time of four years, found that inflammatory markers (IL-6 and CRP) are independent predictors of heart failure from obesity." (PMID 33299523, 2020).
Obesity (continued). "Acute peripheral or central infusion of IL-6 does not affect food intake, even though IL-6 knockout mice develop late-onset obesity due to reduced energy expenditure." (PMID 33255553, 2020). "Obesity can trigger an immune response by producing cytokines such as tumor necrosis factor α (TNF-α), IL-6, and IL-1, initiating an acute immune response, further suggesting the possibility to induce inflammatory responses inducing a progression of periodontal disease." (PMID 32344600, 2020). "Moreover, the secretion of proinflammatory cytokines like TNF-α, IL-6, and MCP-1 promotes JNK, IKK-β/NF-κB, and inducible iNOS pathways, further enhancing the inflammatory process induced by obesity, facilitating the development of insulin resistance." (PMID 32806722, 2020). "Similar to obesity, aged ATMs display an elevated expression of the chemokine receptor CCR2, possessed enhance secretion of pro-inflammatory cytokines IL-6, MCP-1, and TNFα, and a decrease in expression of PPARγ, which mechanistically accounts for the loss in M2 ATMs." (PMID 32499756, 2020). "ATMs are a prominent source of inflammatory cytokines, such as IL1β, IL6 and tumour necrosis factor α (TNFα) and chemokines such as MCP1 that are important contributors to insulin resistance and overall metabolic syndrome in obesity." (PMID 32403975, 2020). "The median decrease of hs-CRP and IL6 was consistent among various pro-inflammatory phenotypes such as diabetes, smoking, obesity and independent of statin use." (PMID 32866166, 2020). "Additionally, Blautia has been described to exhibit closely positive correlation with TG, TC, IL-6, TNF-α and IL-1β, linking to hepatic lipogenesis and obesity." (PMID 33390939, 2020). "Although obesity is considered a low-grade systemic inflammatory state, in the present study, we did not observe differences in us-CRP and in most of the cytokines analysed in blood serum (IL-6, TNF-α, IL-1β, IL-10, MCP-1 and leptin)." (PMID 33489104, 2020). "The level of IL-6, TNF-α, and other pro-inflammatory mediators were elevated in obesity people." (PMID 32596152, 2020). "Therefore, IL-6 is not only involved in the communication between skeletal muscle and adipose tissue, but also involved in the crosstalk between the pancreas and liver to control glucose metabolism and the cardiovascular system, which, in turn, may control sarcopenia and obesity." (PMID 31941015, 2020). "Although the levels of IL-6 have been clearly demonstrated to be increased in relation to obesity, we reported that class II obesity group did not have a statistically significant change in levels of that cytokine." (PMID 32893859, 2020). "Interestingly, IL-6, for which DIO-mediated increases were reverted by Abn-CBD in our study, has been found to play an important role in obesity-induced liver inflammation." (PMID 32210914, 2020). "In obesity, the adipocyte is dysfunctional with excessive production and secretion of pro-inflammatory adipokines, such as tumor necrosis factor α (TNF-α), interleukin 6 (IL-6), and leptin." (PMID 33597945, 2020). "Although there are different opinions on the effects of IL6 in T2DM, recent studies showed that the absence of IL6 resulted in hyperglycemia and higher fat levels in people with obesity." (PMID 33150068, 2020). "IL-6 KO may prevent HFD-induced BMSCs exhaustion and the creation of a senescent BM microenvironment, thereby relieving bone fragility in HFD-induced obesity." (PMID 33679606, 2020). "In contrast, class II obesity showed no statistically significant change in levels of IL-6 and IL-12 versus normal control group." (PMID 32893859, 2020). "The mRNA levels of obesity-related inflammation genes like F4/80, TNFα, CD11c, MCP1 and IL6 were lower in these SOD3-administered mice and hepatic de novo lipogenesis genes like SREBP1c, fatty acid synthase and Scd1 were higher in mice that were just given a high fat diet." (PMID 32903449, 2020).